CCND1 (cyclin D1)
Diseases named in the same sentence as CCND1 in open-access papers (continued):
Sharing a sentence is not in itself a finding about the gene and the disease.
nasopharyngeal carcinoma (52 papers, 2006 to 2025). A carcinoma arising from the nasopharyngeal epithelium. "Nasopharyngeal carcinoma shows up to five mutations including DN-P63, P27, cyclin D1 and BCL-2 associated with its development and manifestation which is consistent with our convexity-upwards log-log model." (PMID 40720480, 2025). "Recently, there have been a number of studies on the association between cyclin D1 G870A polymorphism and nasopharyngeal carcinoma risk." (PMID 24222746, 2013). "However, a definitive conclusion between CCND1 G870A polymorphism and risk of nasopharyngeal carcinoma (NPC) remains elusive." (PMID 25409185, 2014). "Thus, we performed a meta-analysis to explore more precisely the association between cyclin D1 G870A polymorphism and the risk of nasopharyngeal carcinoma." (PMID 24222746, 2013). "Metformin effectively inhibits nasopharyngeal carcinoma cell proliferation by inducing G1 cell cycle arrest, downregulating cyclin D1, and suppressing mTORC1 signaling through AMPK activation." (PMID 40387523, 2025). "According to a reseatch conducted in 2014, SHP-1 (protein tyrosine phosphatase 1 containing SH2 structure) can up-regulate the production of Cyclin D1, hence increasing the cycle of nasopharyngeal cancer cells." (PMID 37940975, 2023). "Cyclin D1 overexpression is considered a crucial prognostic marker for HNCs, especially with laryngeal and nasopharyngeal cancers." (PMID 37568710, 2023). "In nasopharyngeal carcinoma, it inhibits tumor growth and development by regulating cyclin D1 expression." (PMID 38002064, 2023). "In summary, this study confirmed that the EN1‐COL22A1‐CDK4/6‐Cyclin D1‐Rb signalling axis can regulate the cellular senescence of nasopharyngeal carcinoma." (PMID 36196630, 2022). "The results showed that icaritin downregulated the expression of cyclin D1, CDK2, and CDK4 in a dose-dependent manner, further demonstrating that icaritin caused S-phase arrest in nasopharyngeal carcinoma cells." (PMID 36467051, 2022). "Cyclin D1 has also been implicated in nasopharyngeal carcinoma (NPC), resulting in cell survival by the cyclin D1-dependent DNA repair machinery." (PMID 32872659, 2020). "Overexpression of miR-188 inhibits cell proliferation, tumor colony formation and G1/S cell cycle transition in human nasopharyngeal carcinoma CNE cells by inhibiting CCND1, CCND3, CCNE1, CCNA2, CDK4 and CDK243." (PMID 27708404, 2016). "The results of our case-control study showed that the A allele of the CCND1 G870A polymorphism might be associated with nasopharyngeal carcinoma (NPC) in the Chinese population." (PMID 25409185, 2014). "BLU inhibits growth of nasopharyngeal carcinoma cells by regulation of the JNK-cyclin D1 axis to exert tumor suppression." (PMID 22727408, 2012). "Similarly, miR-150 acted as a tumor suppressor in nasopharyngeal carcinoma to repress cell viability and G1/S phase transition by regulating CCND1 and CCNE2." (PMID 33817286, 2020). "For example, miR-138 inhibited nasopharyngeal carcinoma growth by targeting CCND1 oncogene." (PMID 28740507, 2017). "At the same time, the overexpression of CDK4 is a poor prognostic factor of nasopharyngeal carcinoma (NPC) and influences tumor progression by regulating the p21/CCND1/CDK6/E2F1 signaling pathway." (PMID 36292719, 2022). "We previously proved that cyclin D1 was upregulated in nasopharyngeal carcinoma (NPC) and promoted the NPC cell proliferation." (PMID 32697404, 2020). "Cyclin D1 is overexpressed in over 90% of nasopharyngeal carcinoma (NPC) and CCND1 gene activation plays a critical role in NPC pathogenesis." (PMID 29789630, 2018). "Highly expressed EWSAT1 in human nasopharyngeal carcinoma tissues and cell lines increases the expression of miR-326/330-5p clusters that target the gene cyclin D1, ultimately regulating NPC development and progression." (PMID 29719633, 2018).
nasopharyngeal carcinoma (continued). "Overexpression of ZNF671 in nasopharyngeal cancer (NPC) cells induced S phase arrest by upregulating p21 and downregulating cyclin D1 and c-myc." (PMID 39595048, 2024). "Recently, ZNF488 was reported as an oncogenic protein in nasopharyngeal carcinoma growth and invasion by activation of collagen IV/FAK/AKT/Cyclin D1 pathway and epithelial mesenchymal transition." (PMID 37986084, 2023). "In nasopharyngeal carcinoma (NPC), Pin1 inhibition reduced NPC cell proliferation, colony formation and anchorage-independent growth through the decrease of cyclin D1 expression and the activation of caspase-3." (PMID 32258027, 2020). "BLU inhibits clonogenic growth of nasopharyngeal carcinoma cells, arrests cell cycle at G1 phase, downregulates JNK and cyclin D1 promoter activities, and inhibits phosphorylation of c-Jun." (PMID 22727408, 2012). "Cyclin D1 and p16 are involved in the regulation of G1 checkpoint and may play an important role in the tumorigenesis of nasopharyngeal carcinoma (NPC)." (PMID 16953893, 2006). "The control nasopharyngeal carcinoma CNE-2Z cells expressed ClC-3 (red) and cyclin D1 (blue)." (PMID 27451945, 2016). "Two core networks were generated by hub gene screening using the MCODE plugin of Cytoscape, and AKT1, CTNNB1, HSP90AA1, ESR1, CCND1, and EGFR were identified as key hub proteins, which may play an important role in the efficacy of icaritin in the treatment of nasopharyngeal carcinoma." (PMID 36467051, 2022).
adenoma (51 papers, 2002 to 2025). A neoplasm arising from the epithelium. "Mutated/decreasedTumor suppressor protein encoded by CDC73 gene.Function: repression of cyclin D1 (cell cycle halt).Detectable by IHQ.1–6% overlap in mutations with PT adenomas." (PMID 40149663, 2025). "The most common genetic mutation responsible for formation of sporadic adenomas is cyclin D1/PRAD1 gene mutation and was found in 20–40% of patients." (PMID 36013465, 2022). "Among men in the HPFS, the influence of CCND1 genotype on the relation between family history and adenoma risk in the HPFS was statistically significant (P for interaction=0.02)." (PMID 16495921, 2006). "This improves accuracy and can involve using proliferation markers, such as Ki-67 and cyclin D1, to differentiate between parathyroid carcinoma and adenoma." (PMID 40729208, 2023). "The positive expression rates of cyclin D1 were 8.7% (2/23), 33.3% (8/24), 17.4% (4/23), and 38.5% (10/26) in the control tissue, adenoma, EGC, and AGC, respectively (p = 0.061)." (PMID 35723316, 2022). "The highest fraction of cyclin D1-expressiong cells in multiglandular parathyroid disease exceeds the levels seen in adenoma hypothetically suggesting that cyclin D1 represents as an early molecular driver in parathyroid cell proliferation." (PMID 35805976, 2022). "Expression of cyclin D1 shows remarkable intertumoural heterogeneity, both in adenomas and carcinomas as well as significant intralesional heterogeneity with presence of cold and hot spots that closely resembles the patterns of Ki-67 and p21 expression." (PMID 35805976, 2022). "Among adenomas, those with villous histology had a proliferation LI similar to tubular and tubulovillous adenomas, but had higher cyclin D1 levels." (PMID 34762658, 2021). "Other studies have shown that Ki-67 and cyclin D1 levels are higher in carcinomas compared to adenomas." (PMID 34762658, 2021). "Cyclin D1 LI, p16 LI and p21 LI were lower in adenomas compared to serrated lesions, while expression of both BCL2 and BAX were higher (p <0.001)." (PMID 34762658, 2021). "Adenomas were found to have lower LIs of the pro-proliferative cyclin D1 protein and anti-proliferative proteins p16 and p21 as contrasted with serrated lesions." (PMID 34762658, 2021). "Among adenomas, cyclin D1 LI and p16 LI levels increased with greater villous component, and the highest BAX expression was detected in adenomas larger than 2 cm (both p<0.0001)." (PMID 34762658, 2021). "In particular, gene amplification and/or overexpression of CCND1 have been associated with poor prognosis and reduced overall survival in CC patients whereas BCL2L1 has been shown to play a role in the adenoma-to-carcinoma progression." (PMID 29755661, 2018). "Heterogenic, significantly (p < 0.05) increased nuclear Cyclin D1 expression (representative scoring values: +2; +3) was detected in epithelial compartment of adenomas (Q score: 80.00 ± 17.88) and CRCs (Q score: 129.50 ± 45.85)." (PMID 28289479, 2017). "Despite this, few studies investigated its role in pituitary adenomas, only two studies have observed the overexpression of CCND1 in adenomas compared with normal pituitary tissue." (PMID 28382019, 2017). "(F) Western blotting for p-Smad2/3, p21, Axin1, β-Catenin, Cyclin D1 in adenomas of WT and miR-31−/− mice resulting from AOM-DSS treatment." (PMID 28870287, 2017). "Nuclei of epithelial cells of one atypical hyperplasia observed at 750 ppm, two atypical hyperplasias and one adenoma observed at 1500 ppm were positive for cyclin D1." (PMID 26899729, 2016).
adenoma (continued). "In APC-deficient adenoma, accumulation of β-catenin complexed with nuclear TCF4 results in the increased expression of its oncogenic target genes, such as cyclin-D1 that promotes intestinal cell proliferation and polyp formation." (PMID 26500891, 2015). "We find that beta-catenin and related proliferative and apoptotic factors (cyclin-D1, bcl-2, caspase-3, and Ki-67) are expressed early in the sequence, in adenomas." (PMID 23476634, 2013). "IGF2, p27, cyclin D1, and Ki-67 were the markers for which the percentage of stained area was significantly higher in carcinoma samples than in adenoma samples." (PMID 23925558, 2013). "Compared with nonneoplastic mucosa, there was significantly increased staining for bcl-2, caspase-3, and cyclin-D1 in all adenomas combined (χ2 > 25, P < 0.01)." (PMID 23476634, 2013). "We have shown that cyclin D1, and Cdk4 expression is markedly reduced in mature epithelium at the luminal surface but clearly present within adenomas." (PMID 23530816, 2013). "Overall, we find that beta-catenin and related proliferative factors (cyclin-D1 and Ki-67) are overexpressed in adenomas." (PMID 23476634, 2013). "Since cyclin-D1 is a downstream target of beta-catenin, we expected cyclin-D1 expression to be increased in both adenomas and carcinomas." (PMID 23476634, 2013). "IRS for Cyclin-D1 in adenomas compared to normal mucosa was 3.7 (± 0.1) vs. 1.4 (± 0.2) in the control group (H2O) compared to 3.7 (± 0.1) vs. 1.9 (± 0.1) in the TRD group (P ≤ 0.001)." (PMID 20442801, 2010). "In concordance with immunohistochemistry results, Epfn gene expression was increased in the parathyroid gland and inversely decreased in the adenoma, while the expressions of PTH and CCND1 were upregulated, and interestingly, the expression of CaSR was diminished in the adenoma." (PMID 40164571, 2025). "However, they also disregarded overexpression of cyclin D1 as a marker for differential between parathyroid carcinoma versus adenoma." (PMID 35805976, 2022). "However, this inversion is seen in lower frequency than the overexpression of the relevant cyclin D1 protein, e.g., 5–8% vs. 40% in adenomas." (PMID 35805976, 2022). "The detected total protein level alteration along the adenoma-carcinoma transition of the analyzed colorectal tissue samples was fundamentally constituted by the increased epithelial cyclin D1 expression (adenoma ΣQ score: 96.25 ± 18.75 and CRC ΣQ score: 147.00 ± 48.94." (PMID 28289479, 2017). "Cyclin D1 levels also decreased in large adenomas after feeding mice with lingonberries." (PMID 26840292, 2016). "In large adenomas, cloudberries decreased levels of nuclear β-catenin and cyclin D1." (PMID 26840292, 2016). "Deletion of myeloid EP4 receptors led to markedly decreased adenoma ERK phosphorylation, in association with inhibition of tumor cell proliferation, as indicated by significantly reduced expression levels of adenoma cyclin D1 and ki67 as well as c-Myc." (PMID 26378024, 2015). "In addition, higher expression of Ki-67, lower expression of p27kip1, and cyclin D1 overexpression have been demonstrated in carcinomas versus adenoma/hyperplasia." (PMID 23936709, 2013). "Additionally, Cyclin-D1 was strongly expressed (expression > 50%) in 78.6% (n = 22/28) of the gonadotroph adenomas and in 65.5% (n = 19/29) of the null cell adenomas compared to only 20% of corticotroph (n = 2/10) and 20.8% of somatotroph (n = 5/24) adenomas." (PMID 36292101, 2022). "Another immunohistochemical study was performed in 380 adenomas for differences in molecular Ki-67, COX-2, TGFβRI, EGFR, β-catenin, cyclin D1, c-MYC and TUNEL (apoptosis) mutations of proximal and distal adenomas, which may contribute for cancer heterogeneity between the two topographies." (PMID 33759958, 2021). "In addition, CCND1 genotype did not confer a significant elevation in the risk for either large (⩾1 cm) vs small (<1 cm) adenoma in either cohort (data not shown)." (PMID 16495921, 2006).
adenoma (continued). "Cyclin D1 staining of MYO1E WT and MYO1E KO tumors obtained from 16 week old mice revealed a pattern of expression similar to that of carcinomas and adenoma/MIN, respectively." (PMID 27329840, 2016). "At the premalignant stages of PyMT tumor progression (hyperplasia and adenoma/MIN), Cyclin D1 is present mainly in the mammary ducts and the peripheral cells of tumor acini." (PMID 27329840, 2016). "In this study, Riccardin D prevented adenoma growth and induced apoptosis of intestinal polyps by decreasing of PCNA and cyclin D1 in APCMin/+ mice." (PMID 22432006, 2012). "The cell cycle regulator Cyclin-D1 and the transcription factor SOX9 displayed a significantly increased expression in adenomas compared to normal mucosa." (PMID 20442801, 2010). "Consequently, β-catenin drives the expression of Wnt target genes such as MYC, CCND1 (cyclin D1), and AXIN2, promoting uncontrolled cell division and, subsequently, the development of adenomas and carcinomas." (PMID 39684219, 2024). "In this study, the expression levels of epidermal growth factor receptor (EGFR) and cyclin D1 were assessed in 96 tissue samples, including non-tumorous tissue, adenoma, and carcinoma." (PMID 35723316, 2022). "Moreover, when inactivation of RhoA signaling by transducing dominant-negative form of RhoA resulted in larger adenomas and decreased survival in a zebrafish model of KRAS-induced hepatic adenoma by rising AKT/S6 signaling and cyclin D1." (PMID 32244355, 2020). "We found cyclin D1 immunostaning with adenoma and malignant subtypes and absence of immunostaining with normal thyroid and AG." (PMID 30885146, 2019). "A variety of genetic alterations including CCND1 amplification, alterations of the PI3K/AKT/mTOR pathway and overexpression of CCND1 (previously PRAD1) have been identified by high-throughput genetic screening in parathyroid carcinoma and adenoma." (PMID 30140036, 2018). "CCND1 is more strongly expressed in nonfunctional PA than in functional PA, in macroadenoma than in microadenoma, and in recurrent adenoma than in nonrecurrent adenoma." (PMID 28577032, 2017). "The pattern of Cdk4 and cyclin D1 staining was strongest in the crypts and adenomas and almost absent from the villi." (PMID 23530816, 2013). "A previous study on FAP adenomas showed 40%(±20%) expression of cyclin-D1 in adenomas, compared with no expression in nonneoplastic mucosa; however, no carcinomas were studied." (PMID 23476634, 2013). "Immunhistochemistry revealed increased expression of Ki-67, β-catenin, SOX9 and Cyclin-D1 in adenomas compared to normal mucosa – without significant difference between TRD and control treatment." (PMID 20442801, 2010). "Our previous research indicated that the Wnt pathway score (the sum of scores for nuclear b-catenin, c-Myc, and Cyclin D1) significantly correlated with larger tumor size, villous growth pattern, and advanced adenomas but not metachronous adenoma, which are consistent with this study." (PMID 39977302, 2025). "Moreover, in keeping with the proliferative property of tumor cells, cyclin D1 was highly expressed in all adenomas, regardless of the FHL2 genotype." (PMID 20442768, 2010). "In the tumor group (adenoma, EGC, and AGC), the positive expression rate of cyclin D1 was high compared to the control group (non-tumorous tissue) (30.1% (22/73) vs. 8.7% (2/23), p = 0.038)." (PMID 35723316, 2022). "Analysis of cyclin D1, TGF-β, and beta catenin expression shows that cyclin D1 expression was increased in all adenomas, regardless of diet." (PMID 26959117, 2016). "The mRNA levels of cyclin D1 and c-myc were indistinguishable in nontumor intestine between ApcΔ14/+FHL2+/+ and ApcΔ14/+FHL2−/− animals, and were strongly increased in adenomas from mice of both genotypes." (PMID 20442768, 2010).